ARTN (artemin)
Diseases named in the same sentence as ARTN in open-access papers (continued):
Sharing a sentence is not in itself a finding about the gene and the disease.
tumor (continued). "The increase in anchorage independent growth by ARTN suggested that ARTN may promote self-renewal or tumor-initiating capacity (TIC)." (PMID 26675549, 2016). "Moreover, ARTN also enhanced tumorsphere formation and the tumor initiating capacity of HCC cells, consequent to expansion of the CD133+ CSC population." (PMID 26675549, 2016). "It seems contradictory that miR-223 can suppress tumor invasion and metastasis through targeting Artemin, but may promote tumor by inhibiting the expression of EPB41L3, a tumor suppressor in human NPC." (PMID 26055874, 2015). "In addition to the role of neurotrophic factor, ARTN has also been found to have an oncogenic role in promoting tumor growth, migration, invasiveness and metastasis in a number of types of human cancer." (PMID 25120606, 2014). "Interestingly, miR-223 was found to have a tumor suppressor function by inhibiting migration and invasion through targeting Artemin, a tumor metastasis-related gene, in human esophageal carcinoma." (PMID 24899581, 2014). "Interestingly, also a number of oncogenes is up regulated by E2 (MERTK, RET and its ligand ARTN), and several (putative) tumor suppressor genes are down regulated by E2 (BLNK, LATS2, RPRM) that are not, or less, regulated by EGF." (PMID 24758408, 2014). "ARTN sensitive cancers of varying origin may also utilize different ARTN binding receptors, or different combinations thereof, to promote tumor progression." (PMID 23351331, 2013). "ARTN therefore co-ordinately regulates multiple aspects of tumor growth and metastasis." (PMID 23185544, 2012). "ARTN therefore co-ordinately regulates processes promoting tumor growth and metastasis." (PMID 23185544, 2012). "We provided strong evidence that supports a role for ARTN in tumor cell migration and invasion." (PMID 21453483, 2011). "In addition, recent studies have suggested a role for ARTN in tumour invasiveness and angiogenesis." (PMID 39684220, 2024). "In addition to the commonly studied cellular components of TIME, immune modulating molecules like TGF-β1, IDO, and Artemin in the ECM have also been considered as important parts of STIE in local tumor, and to play critical roles in cancer development and cancer immunity." (PMID 35799264, 2022). "However, the clinical utility of targeting artemin or its signaling as the modulation of tumor growth-promoting effects of EPCs is unknown." (PMID 33669537, 2021). "Moreover, EPCs promote tumor growth by the secretion of growth factors, including artemin." (PMID 33669537, 2021). "Additionally, ARTN dramatically increased xenograft tumor size and metastasis in vivo." (PMID 26675549, 2016). "Thus, ARTN co-ordinately regulates angiogenesis and tumor progression of ER-MC." (PMID 23185544, 2012). "Thus, ARTN stimulates de novo tumor angiogenesis mediated in part by VEGF-A." (PMID 23185544, 2012). "Thus expression of ARTN in ER-MC cells promotes tumor angiogenesis in vivo." (PMID 23185544, 2012). "Similarly, ARTN could potentially modulate not only tumor growth and metastasis, but also promote angiogenesis as a contribution to tumor progression leading to poor survival outcomes in ER-MC." (PMID 23185544, 2012). "Thus, ARTN modulation of endothelial cell behaviour promoting de novo angiogenesis may occur as part of a co-ordinated tumor growth process involving cells with CSC-like behaviour." (PMID 23185544, 2012). "Concurrently, genes promoting tumor growth, including HES4, YBX1, and ARTN, were also upregulated in hmmyCAFs." (PMID 41057994, 2025). "Intriguingly, study has been demonstrated that both local tumor radiation and anti-PD-L1 treatment reduced CD45−EPCs via a remote effect to reduce artemin." (PMID 37208766, 2023). "Hou et al25 showed that the presence of LM increased tumor-induced CD45−Ter119+CD71+ erythroid progenitor cells, leading to overproduction of artemin, a neutrophic peptide." (PMID 38051531, 2023).
tumor (continued). "Tumor-inducible, erythroblast-like cells (Ter-cells) with Ter-119+CD45−CD71+ markers deriving from megakaryocyte–erythroid progenitor cells produces Artemin in the spleen and leads high level of Artemin in the blood." (PMID 35799264, 2022). "Forced expression of ARTN in CRC cells enhanced oncogenic behavior, mesenchymal phenotype, stem cell-like properties and tumor growth and metastasis in a xenograft model." (PMID 34422665, 2021). "The genes that appeared most frequently among the top projected targets for the 15 patient tumor samples were SLC24A1, ARTN, DHRSX, TEX261, and FRMD8." (PMID 34662337, 2021). "To determine the potential in vivo role of ARTN secreted from ER-MC cells in tumor angiogenesis, we injected MDA-MB-231-ARTN cells into the mammary fat pad of immunodeficient nude mice." (PMID 23185544, 2012). "Moreover, our studies also revealed that Artemin significantly inhibited the killing effect of CD8+ T cells on tumor cells and reduced the effects of radiotherapy and PD-L1 inhibitor therapy on tumor growth." (PMID 35799264, 2022). "Our results suggest that exogenous estrogen might promote tumor growth by inducing GPER and ARTN expression in OVX models." (PMID 34257587, 2021). "Survival outcome in patients whose tumor expressed both ARTN and SDC3 was not significantly different to those patients who were negative for both proteins." (PMID 23351331, 2013). "Indeed, similar to ARTN, VEGF-A has been reported to promote cancer cell proliferation and metastasis, tumor growth, CSC-like behaviour, and angiogenesis." (PMID 23185544, 2012). "In addition, ARTN regulates the cancer stem cell population (CSC-like cell population), which has the ability to promote tumor-initiating capacity and increase radio- and chemo-resistance, which may be responsible for metastasis and palindromia." (PMID 36471885, 2022). "Downstream signaling of artemin promotes the phosphorylation of extracellular signal-regulated kinase (ERK), protein kinase B (AKT), and caspase-9, promoting proliferation and invasiveness, while preventing apoptosis in tumor cells, even induced by the therapy." (PMID 33669537, 2021).
cancer (32 papers, 2011 to 2025). A tumor composed of atypical neoplastic, often pleomorphic cells that invade other tissues. "It was observed that the ARTN gene exhibited significant DE between myeloid cells 2 and carcinoma-associated fibroblasts (p-value = 1)." (PMID 40686838, 2025). "Recent studies have shown that increased serum artemin concentration and receptor expression are associated with poor prognosis in cancer patients." (PMID 36567722, 2022). "Artemin (ARTN) is a growth factor associated with the tumorigenesis and progression of human cancers." (PMID 35205115, 2022). "As a member of the glial cell line-derived neurotrophic factor ligand family, ARTN is associated with many malignant tumors." (PMID 34496868, 2021). "Further understanding of the role of ARTN in a tissue‐specific manner and its underlying signalling mechanisms will help us to develop ARTN as a therapeutic target for neurological diseases and cancers." (PMID 32573073, 2020). "ARTN and NRTN genes are expressed most abundantly in osteoblastic OS cells, GDNF in carcinoma associated fibroblasts, and PSPN in endothelial cells." (PMID 40686838, 2025). "And cell function experiments also confirmed the ability of ARTN, a gene characteristic of the stemness subtype model, to promote cancer and maintain cancer cell stemness." (PMID 37674202, 2023). "When an initial damage to the nerves by cancer cell, neurons and/or SCs produce Artemin/GFRα3 to repair the nerves, but the abundance of Artemin attracts further cancer cells to the site of injury, which produces a vicious cycle." (PMID 36900158, 2023). "Among genes expressed only in OVX with E2 group, artemin (ARTN) was known as a factor involved in the cancer progression." (PMID 34257587, 2021). "Elevated expression of ARTN has been observed in multiple human cancers including endometrial, lung, mammary, liver and pancreatic carcinoma." (PMID 34422665, 2021). "This would contribute to increased viability of the detached mesenchymal-like cancer cells (as observed by enhanced anchorage independent growth), which together with enhanced invasiveness would mediate ARTN promoted metastasis." (PMID 34422665, 2021). "Increased ARTN expression in mammary carcinoma also promotes cancer stem cell-like behavior and acquired resistance to both chemo- and targeted- therapies." (PMID 34422665, 2021). "Artemin also has protumorigenic activity and promotes cancer cell survival, proliferation, migration, and invasiveness." (PMID 33669537, 2021). "Accumulating evidence indicates that ARTN possesses a critical role in cancer cell population adaptability to hostile challenges such as antiestrogens, Trastuzumab, chemotherapeutics and ionizing radiation." (PMID 26675549, 2016). "The adaptive response mediated by ARTN to these therapeutic approaches involves an increase in the cancer stem cell population." (PMID 26675549, 2016). "It was observed that the ARTN gene exhibited no significant DE between carcinoma associated fibroblasts and endothelial cells (P-value = 3.76 × 10−1)." (PMID 40686838, 2025). "The ARTN gene was not DE between osteoclasts and carcinoma associated fibroblasts (P-value = 1.43 × 10−2)." (PMID 40686838, 2025). "Our results showed that the ARTN gene exhibited no significant DE between plasmocytes and carcinoma associated fibroblasts (P-value = 8.183 × 10−2)." (PMID 40686838, 2025). "Moreover, increased serum artemin concentrations, as well as increased expression of its receptors, correlate with poor prognosis in cancer patients." (PMID 33669537, 2021). "However, the mechanism by which ARTN is differentially expressed and involved in various types of cancers warrants further investigation." (PMID 32573073, 2020). "The emerging role of ARTN in cancers and therapeutic resistance to cancers is also explored." (PMID 32573073, 2020). "ARTN, therefore, emerges as a potential therapeutic target for regenerative medical applications in the treatment of spinal cord injury, neuropathic pain and cancers." (PMID 32573073, 2020).
cancer (continued). "Similarly, Glial cell line–Derived Neurotropic Factor (GDNF) and artemin (ARTN), released by cancer, increase TRPV1 expression and thus pain sensibility." (PMID 31248001, 2019). "In addition, previous studies have suggested that ARTN has a role in the development and progression of diverse human carcinoma." (PMID 25120606, 2014). "It is also possible that further proteins that bind ARTN are yet to be identified and may also participate in the oncogenic functions of ARTN in various cancer types." (PMID 23351331, 2013). "Furthermore, ARTN promotes epithelial to mesenchymal transition and angiogenesis and enhances cancer stem cell like behaviour in ER-negative MC (ER-MC) carcinoma cells resulting in metastatic dissemination." (PMID 23351331, 2013). "Accumulating evidence is suggesting that ARTN is involved in cancer metastasis." (PMID 21453483, 2011). "That increased ARTN expression induces genes associated with EMT and stimulates metastasis of ER-MC suggests that it may regulate a cancer stem cell-like sub-population of cells that possess an enhanced ability to metastasize to distant organs." (PMID 22060274, 2011). "Future studies should examine how miR-223 is regulated in human cancer and other human diseases and whether both ARTN and miR-223 are targets for therapy." (PMID 21453483, 2011). "Furthermore, the ARTN gene was not DE between osteoblastic OS cells and carcinoma-associated fibroblasts (P-value = 1)." (PMID 40686838, 2025). "Furthermore, the ARTN gene was not DE between myeloid cells 1 and carcinoma-associated fibroblasts (P-value = 2.5 × 10−15)." (PMID 40686838, 2025). "Hence, ARTN expression in CRC cells promoted a cancer stem-like phenotype." (PMID 34422665, 2021). "Furthermore, targeting CDH2 may be an alternative or combination strategy to inhibit progression of ARTN dependent cancer." (PMID 34422665, 2021). "In addition, the emerging role of ARTN in various types of cancers is surveyed." (PMID 32573073, 2020). "Conversely, neural structures release factors such as NGF, GDNF, ARTN, and CXCL12 (SDF-1), which act as chemoattractants for cancer cells expressing corresponding receptors." (PMID 40909268, 2025). "The results of cell function experiments showed that ARTN can promote the proliferation, invasion, and migration of NSCLC and is closely related to cancer stem cell properties." (PMID 37674202, 2023). "Artemin activates the glial cell-derived neurotrophic factor (GDNF) family receptor alpha-3 (GFRα3) and its co-receptor RET on cancer cells." (PMID 33669537, 2021). "Higher intensity of ARTN expression was observed in CRC tissue specimens, both in the myoblasts and the carcinoma cells (right)." (PMID 34422665, 2021). "Cancer cells secrete factors such as NGF, ARTN, CXCL12/SDF-1 which attract Schwann cells, and Schwann cells secrete GDNF, TGF-β and provide NCAM-1-mediated cell-cell interaction to promote cancer cell migration and aggressiveness." (PMID 33050151, 2020). "In PAAD, over-expressed neurotrophin (NRTN) and Artemin activate RET tyrosine kinase (TK) by binding their homologous GDNF family receptor -α (GFRα) receptors, promoting cancer cell invasion and neuronal plasticity, and promoting the proliferation of nerve fibers around the tumor." (PMID 36900158, 2023). "Given that Hep3B and HepG2 cells are all cancer cell lines, we further explored the functional role of ARTN in immortalized and non-transformed human liver cells." (PMID 26675549, 2016). "We therefore next explored whether ARTN regulated the signaling pathways involved in CSC and EMT, which are considered to be critical steps for cell motility and cancer metastasis." (PMID 26675549, 2016). "However, to promote cancer activity, they also target different genes including C/EBPβ, FOXO1, NFI-A, STAT5A, ARTN, FBXW7, and SEPT6 (for miR-223) and FUS1, RhoC, PTEN, CDKN1A, TGFβR2, and NRF2 (for miR-93)." (PMID 26273679, 2015).
cancer (continued). "Herein, the functional role of ARTN in CRC progression has been determined and demonstrated that ARTN promotes progression of CRC by p44/42 MAPK dependent expression of CADHERIN 2 (CDH2, also known as N-CADHERIN) which promotes epithelial-to-mesyenchymal transition and cancer cell metastasis." (PMID 34422665, 2021). "Hence, ARTN apparently exerts differential functional properties in normal liver cells compared to cancer cells." (PMID 26675549, 2016). "Although chemokines and neurotrophic factors with chemoattractive properties such as NGF, GDNF, artemin, or neurturin have long been studied in the context of NI in PDAC, the cytoskeletal adaptations of cancer cells during their nerve-directed migration have not been in the focus." (PMID 37607005, 2023).
neurological disorders (2 papers, 2019 to 2020). "In additional to SCI, increasingly data have implicated a role of ARTN in other neurological disorders." (PMID 32573073, 2020). "This review discusses the role of ARTN in spinal cord injury repair, neuropathic pain and other neurological disorders." (PMID 32573073, 2020). "This review discusses the role of ARTN in spinal cord injury, neuropathic pain and other neurological disorders." (PMID 32573073, 2020). "As NCAM plays a significant role in neurodevelopment, regeneration, and synaptic plasticity we suggest that ARTN and its mimetics are promising candidates for treatment of neurological disorders and warrant further investigations." (PMID 30853893, 2019).
psychiatric disorder (2 papers, 2019 to 2025). A disorder characterized by behavioral and/or psychological abnormalities, often accompanied by physical symptoms. "(iii) Two of the highlighted genes in this study, ARTN and C2orf82, have previously been associated with other psychiatric disorders." (PMID 31582733, 2019).
ARTN also shares sentences with these, for which no sentence is quoted: generalized anxiety disorder (2 papers); anemia (1); benign breast disease (1); bipolar disorder (1); bone cancer (1); cervical adenocarcinoma (1); cervical squamous cell carcinoma (1); Cirrhosis (1); COVID-19 (1); dermatitis (1); infection (1); leukemia (1); lymphoma (1); medulloblastoma (1); monocytic leukemia (1); neuroblastoma (1); osteomyelitis (1); osteosarcoma (1); ovarian carcinoma (1); pancreatic ductal adenocarcinoma (1); peripheral nerve injury (1); prostate carcinoma (1); psoriasis (1); rheumatoid arthritis (1); spinal cord injury (1); ulcerative colitis (1).